MIR18A (microRNA 18a)
Synonyms: hsa-mir-18; hsa-mir-18a; C13orf25; MIR18; MIRH1; MIRHG1; MIRN18; MIRN18A; miR-18; miRNA18A; mir-18a
Gene: MicroRNA gene on chromosome 13 (91,350,751 to 91,350,821, forward strand). Ensembl gene ENSG00000283815.
Gene Ontology:
Biological process: miRNA-mediated post-transcriptional gene silencing
Cellular component: RISC complex
Homologues: Orthologues: chimpanzee ptr-mir-18a (100% identical), dog MIR18A (100% identical), guinea pig MIR18A (100% identical), macaque MIR18A (100% identical), pig ssc-mir-18a (100% identical), rabbit MIR18A (100% identical), mouse Mir18 (99% identical), rat Mir18a (99% identical), tropical clawed frog xtr-mir-18a (99% identical), zebrafish mir18a (96% identical), zebrafish mir18b (90% identical), zebrafish mir18c (80% identical). Paralogues in human: MIR17 (58% identical), MIR106B (55% identical), MIR20A (55% identical), MIR20B (52% identical).
Diseases named in the same sentence as MIR18A in open-access papers:
MIR18A is named in the same sentence as 2 diseases in open-access papers, as found by Europe PMC text mining. Sharing a sentence is not in itself a finding about the gene and the disease.
MIR18A shares sentences with these, for which no sentence is quoted: tumor (2 papers); lung carcinoma (1).